DMP1 (dentin matrix acidic phosphoprotein 1)
Description:
May have a dual function during osteoblast differentiation. In the nucleus of undifferentiated osteoblasts, unphosphorylated form acts as a transcriptional component for activation of osteoblast-specific genes like osteocalcin. During the osteoblast to osteocyte transition phase it is phosphorylated and exported into the extracellular matrix, where it regulates nucleation of hydroxyapatite.
Synonyms: DMP-1; ARHP; ARHR
Tractability: Antibody: UniProt places it where antibodies can reach, with high confidence; its Gene Ontology location is reachable by antibodies, with high confidence; UniProt predicts a signal peptide or a membrane-spanning region.
Gene: Protein-coding gene on chromosome 4 (87,650,280 to 87,664,361, forward strand). Ensembl gene ENSG00000152592.
Subcellular location: Nucleus; Cytoplasm; Secreted, extracellular space, extracellular matrix
Pathways (Reactome):
Metabolism of proteins: Post-translational protein phosphorylation; Regulation of Insulin-like Growth Factor (IGF) transport and uptake by Insulin-like Growth Factor Binding Proteins (IGFBPs)
Extracellular matrix organization: ECM proteoglycans
Gene Ontology:
Molecular function: calcium ion binding; extracellular matrix binding; integrin binding
Biological process: extracellular matrix organization; ossification
Cellular component: non-collagenous component of interstitial matrix; endoplasmic reticulum lumen; extracellular matrix; extracellular region; cytoplasm; nucleus
Genetic constraint (gnomAD): Loss-of-function variants: 10 observed, 14.02 expected, observed/expected ratio (o/e) 0.71, 90% interval 0.44 to 1.21. The upper end of that interval is the gene's LOEUF score, 1.21, which puts it in group 5 of 6, group 1 being the genes least tolerant of losing a copy. Missense variants: 528 observed, 615.45 expected, observed/expected ratio (o/e) 0.86, 90% interval 0.8 to 0.92. Synonymous variants: 186 observed, 214.54 expected, observed/expected ratio (o/e) 0.87, 90% interval 0.77 to 0.98.
Homologues: Orthologues: chimpanzee DMP1 (97% identical), macaque DMP1 (90% identical), dog DMP1 (76% identical), pig DMP1 (69% identical), rabbit DMP1 (67% identical), rat Dmp1 (65% identical), mouse Dmp1 (65% identical), guinea pig DMP1 (62% identical).
Diseases named in the same sentence as DMP1 in open-access papers:
DMP1 is named in the same sentence as 104 diseases in open-access papers, as found by Europe PMC text mining. Sharing a sentence is not in itself a finding about the gene and the disease. The quoted sentences say what the papers report.
autosomal recessive hypophosphatemic rickets (33 papers, 2008 to 2025). Autosomal recessive hypophosphatemic rickets (ARHR) is a hereditary renal phosphate-wasting disorder characterized by hypophosphatemia, rickets and/or osteomalacia and slow growth. "Autosomal dominant hypophosphatemic rickets is due to FGF23 variants, while autosomal recessive hypophosphatemic rickets is due to biallelic variants in DMP1, ENPP1, FAM20C or SLC34A3." (PMID 40533633, 2025). "DMP1 is a suppressor of FGF23 as inactivating mutations in DMP1 result in autosomal recessive hypophosphatemic rickets (ARHR), a disease where overproduction of FGF23 results in renal phosphate wasting, osteomalacia, and rickets." (PMID 33716961, 2021). "CATCH identifies a potential causative variant in the gene DMP1, a transcriptional activator of osteoblast-specific genes such as alkaline phosphatase and osteocalcin, already associated to Autosomal Recessive Hypophosphatemic Rickets (ARHR)." (PMID 26415661, 2015). "Recently, we and other groups have demonstrated that mutations in DMP1 result in autosomal recessive hypophosphatemic rickets (ARHR) in humans." (PMID 21542006, 2011). "Loss of function mutations in the human DMP1 gene have been shown to cause autosomal recessive hypophosphatemic rickets in different ethnic groups including Turkish, consanguineous Spanish, Lebanese and Japanese populations." (PMID 21747952, 2011). "Previous research has shown that mutations in the DMP1 gene are responsible for autosomal recessive hypophosphatemic rickets in humans." (PMID 21747952, 2011). "This condition includes several forms: autosomal dominant hypophosphatemic rickets (ADHR) caused by FGF23 mutations, autosomal recessive hypophosphatemic rickets (ARHR) caused by DMP1 mutations, and X‐linked hypophosphatemic rickets (XLH) caused by PHEX mutations." (PMID 40661139, 2025). "The three forms of autosomal recessive hypophosphatemic rickets (ARHR) result from mutations in DMP1 [ARHR1,], ENPP1 [ARHR2,], and FAM20C [ARHR3,], while hypophosphatemic rickets and hyperparathyroidism (HRHPT) is caused by mutations that upregulate KLOTHO expression." (PMID 30808384, 2019). "Additionally, loss-of-function of DMP1 is responsible for autosomal recessive hypophosphatemic rickets, an endocrine disorder marked by low circulating Pi and severe hypomineralization of the bones and teeth." (PMID 30526676, 2018). "Inactivating mutations in the phosphate-regulating gene with homologies to endopeptidases on the X chromosome (PHEX) cause X-linked hypophosphatemic rickets (OMIM 307800), and loss of DMP1 activity results in autosomal-recessive hypophosphatemic rickets (OMIM 241520)." (PMID 22615579, 2012). "Mutations in either PHEX (XLH, X-linked hypophosphatemic rickets) and DMP1 (ARHR, autosomal recessive hypophosphatemic rickets) cause renal phosphate wasting and its clinical sequelae by primary elevations of FGF23." (PMID 35629904, 2022). "Clinically, DMP1 mutation has been shown to result in autosomal recessive hypophosphatemic rickets (ARHP), and one case study described a family with ARHP; owing to a novel homozygous DMP1 mutation, two probands had hearing deficit." (PMID 37106825, 2023). "Autosomal Recessive Hypophosphatemic Rickets (ARHR) type 1 (MIM 241520) and 2 (MIM 613312) are associated with molecular defects in Dentin matrix protein 1 (DMP1) and the ectonucleotide pyrophosphatase phosphodiesterase 1 (ENPP1), respectively." (PMID 34068220, 2021). "Mutations in dentin matrix protein 1 (DMP1) and ectonucleotide pyrophosphatase/phosphodiesterase 1 (ENPP1) results in autosomal recessive hypophosphatemic rickets 1 and 2, respectively." (PMID 29515522, 2018). "For instance, increased serum FGF-23 levels were found in patients with autosomal recessive hypophosphatemic rickets (ARHR), a disease caused by mutation in DMP-1 gene." (PMID 18688277, 2008).
autosomal recessive hypophosphatemic rickets (continued). "Furthermore, mutations in the dentin matrix protein 1 gene (DMP1) were identified in affected animals, and are known to be involved in autosomal recessive hypophosphatemic rickets humans." (PMID 32942601, 2020). "DMP1 mutations in autosomal recessive hypophosphatemic rickets (ARHR) patients and mice lacking Dmp1 display an overlapping pathophysiology, such as hypophosphatemia." (PMID 20499360, 2010).
hypophosphatemia (32 papers, 2010 to 2025). Lower than normal levels of phosphates in the circulating blood. "In vivo, DMP1 deficiency is associated with enhanced Fgf23 expression with hypophosphatemia, and in vitro DMP1 downregulates FGF23 through NFAT signaling." (PMID 35084563, 2022). "Ossicular deterioration in CHL has been demonstrated in other mouse models of FGF23-mediated hypophosphatemia, such as those caused by involvement of Dmp1, a regulator of phosphate homeostasis and mineralization." (PMID 35854274, 2022). "FAM20C can suppress FGF23 production by enhancing DMP1 expression and its inactivation causes FGF23-related hypophosphatemia by decreasing transcription of DMP1, resulting in increased FGF23 levels in patients with Raine’s syndrome." (PMID 29280738, 2017). "ARHR due to the DMP1 mutation is characterized by hypophosphatemia, osteomalacia, and poor bone and tooth development and structure and we have previously shown that FGF23 is elevated in osteocytes similar to what occurs in XLH." (PMID 27242547, 2016). "Dmp1 deficiency is implicated in hypophosphatemia and osteomalacia in humans, while overexpression promotes bone mineralization." (PMID 23451204, 2013). "Dmp1-, Phex- and Fam20c-deficient mice shared similarities in osteomalacia, hypophosphatemia and the remarkable elevation of FGF23 in the circulation and skeleton." (PMID 22615579, 2012). "For both patients with the homozygous DMP1 mutations, blood and urine biochemistries were consistent with hypophosphatemia owing to renal phosphate wasting." (PMID 20499351, 2010). "Homozygous DMP1 mutations result in hypophosphatemia owing to increased renal phosphate excretion and in a severe skeletal phenotype with short stature, deformed bones, abnormal bone structure, pathologic fractures, and severe enthesopathies." (PMID 20499351, 2010). "Although DMP1 is expressed in both hard and soft tissues, the phenotype in human DMP1 mutations or Dmp1 deficient mice was mainly identified in the skeleton and the teeth, likely caused by hypophosphatemia, and increased FGF23 levels." (PMID 22879941, 2012). "The Dmp1 KO phenotype is associated with hypophosphatemia and elevated FGF-23 concentrations." (PMID 21542006, 2011). "The hypothesis was tested by developing and modifying multiple imaging techniques, including both in vivo and in vitro models plus two types of hypophosphatemia rickets models (Dmp1-null and Hyp, Phex mutation mice), and Dmp1-Cre induced high level of β-catenin models." (PMID 34326685, 2021). "This pathologic change could be caused by both the intrinsic osteoblast defect owing to a loss of DMP1 and an indirect role of hypophosphatemia on Dmp1 null osteoblasts because restoration of Pi by injections of Fgf23Ab greatly improves osteoclast numbers and bone remodeling." (PMID 21542006, 2011). "In contrast with the administration of anti-FGF23 antibodies in younger mice, and despite the full correction of hypophosphatemia, 12-week-old Dmp1-null mice showed only a partial rescue of bone growth and mineralization." (PMID 37943605, 2023). "In this respect, osteocytes are one of the primary regulators of systemic phosphate levels through Dmp1 and fibroblast growth factor 23 (FGF23); as in Dmp1 knockout osteocytes, FGF23 is released into the circulation, causing hypophosphatemia." (PMID 37293482, 2023). "Previous studies have shown that dietary Pi supplementation improves bone growth and mineralization in 3- to 7-week-old Dmp1-null mice and that anti-FGF23 antibodies correct hypophosphatemia and bone mineralization in 1- to 4-week-old Dmp1-null mice." (PMID 37943605, 2023). "Mutations in PHEX, DMP1, and FAM20C have been reported to be responsible for FGF23-related hypophosphatemia." (PMID 36776964, 2023). "In aggregate, our study suggests that in addition to hypophosphatemia, FGF23 excess and DMP1 deficiency directly control osteoblast differentiation and mineralization in ARHR pathogenesis." (PMID 37943605, 2023).
hypophosphatemia (continued). "In accordance with previous studies, DMP1 deficiency in Dmp1KO mice increased serum cFGF23, iFGF23, and i/c FGF23 levels, which led to increased FePi, resulting in hypophosphatemia." (PMID 37943605, 2023). "Of these, DMP1 and PHEX are osteogenic marker genes, whose mutations result in hypophosphatemia, low bone mineral density, and elevated FGF23 production." (PMID 35392115, 2022). "A recent study reported that FAM20C supresses FGF23 production by enhancing DMP1 expression and that inactivation mutations in FAM20C cause FGF23 related hypophosphatemia by decreasing transcription of DMP1." (PMID 25928877, 2015). "The phenotypic changes in the Fam20c-conditional knockout mice share many similarities (hypomineralization, elevation of FGF23, hypophosphatemia) with those observed in the PHEX- and DMP1-deficient subjects." (PMID 22615579, 2012). "We hypothesized that reduction of osteocyte-produced FGF23 in Dmp1-null mice might lead to correction of hypophosphatemia and improve bone growth and mineralization, similar to Hyp mice." (PMID 37943605, 2023). "In the present study, we used dietary Pi supplementation and the osteocyte-specific deletion of Fgf23 to correct hypophosphatemia in order to study the respective contributions of FGF23 excess, hypophosphatemia, and DMP1 deficiency to the bone defects in adult Dmp1-null mice." (PMID 37943605, 2023). "Due to this, it appears that DMP1 could negatively regulate FGF23 during bone development and that secondary hypophosphatemia in FGF23 elevation could be the cause of rickets, but osteomalacia depends on other DMP1 functions." (PMID 34360805, 2021). "The skeletal defects of the PHEX- and DMP1-deficient subjects are believed to be due to the combined effects of two factors: 1) the intrinsic defects of the PHEX- and DMP1-deficient cells that prevent them from forming and mineralizing ECM properly and 2) hypophosphatemia." (PMID 22615579, 2012). "Heterozygosity for the DMP1 mutation was associated with mild hypophosphatemia but without clinical evidence of skeletal dysplasia." (PMID 20499351, 2010). "Mice with DMP1 deficiency develop rickets and osteomalacia, including growth plate defects, abnormalities in osteocyte differentiation and the osteocytic canaliculi–lacunae system, an increase of FGF23, mild hypercalcemia with normocalciuria, phosphaturia and severe hypophosphatemia." (PMID 34360805, 2021). "Our results support the hypothesis that hypophosphatemia resulting from PHEX loss-of-function affects the integrity of the organization of the dentin matrix and suggests that exogenous DMP1 can restore physiological processing of matrix proteins, in addition to its canonical role in mineralization." (PMID 32116788, 2020). "In the Dmp1-null mouse model of ARHR, genetic overexpression of a Dmp1 transgene fully rescues FGF23 levels, hypophosphatemia, and bone defects, but studies specifically targeting FGF23 in models of ARHR are scarce." (PMID 37943605, 2023). "Recent researches have shown that the mineralization induced by human cells is disturbed independently of hypophosphatemia and supported a local role for PHEX, DMP1 or FAM20C in matrix mineralization." (PMID 36717535, 2023). "DMP1 knockout mice have displayed increased serum levels of FGF23, hypophosphatemia, skeletal and dental anomalies and osteomalacia." (PMID 29280738, 2017). "Ablation of the Fam20c gene in conditional knockout mice affects tooth and bone development by downregulation of SIBLING family of proteins such as DMP1 and DSPP and by increasing FGF23 in serum and promoting phosphate excretion and hypophosphatemia." (PMID 27187611, 2016). "The inactivation of PHEX/Phex or DMP1/Dmp1 has been shown to result in the increased expression of FGF23/Fgf23, leading to increased renal Pi wasting and hypophosphatemia in both humans and mice." (PMID 24710520, 2014).
hypophosphatemia (continued). "Our data show that both transgenes fully rescue the skeletal abnormalities of Dmp1 null mice as well as normalizing elevated circulating FGF-23 levels and hypophosphatemia." (PMID 20734454, 2011). "In contrast, in the present study, we showed that dietary Pi supplementation, initiated at 6 weeks of age, did not rescue hypophosphatemia or the bone phenotype in 12-week-old Dmp1-null mice." (PMID 37943605, 2023). "While the role of DMP1 as a pro-mineralization factor is well documented, its direct contribution in the pathogenesis of impaired mineralization in ARHR is less clear, as most effects are attributed to failure of DMP1 to suppress FGF23 and FGF23-induced hypophosphatemia." (PMID 37943605, 2023). "Because PHEX, DMP1, and ENPP1 all induce FGF23-related hypophosphatemia, they may affect common pathophysiological mechanisms inducing enthesopathies and spinal ligament ossifications." (PMID 37530996, 2023). "Therefore, correction of hypophosphatemia in the face of residual FGF23 elevations is insufficient to correct the bone phenotype associated with ARHR in the long term and the residual bone phenotype might be due to persistent FGF23 elevations and/or DMP1 deficiency." (PMID 37943605, 2023). "Based on observations that Dmp1 null mice show osteomalacia accompanied by hypophosphatemia and elevated FGF-23 levels, this study set out to further characterize the skeletal abnormalities in Dmp1 null mice and determine the mechanisms responsible for those defects." (PMID 21542006, 2011). "However, mice with high serum levels of FGF23, hypophosphatemia, bone and dentin defects due to FAM20C deficiency are not rescued with DMP1 over-expression." (PMID 34360805, 2021). "A non-phosphorylated DMP1 could produce a non-functional protein or undergo a faster degradation, leading to hypophosphatemia, calcium binding alterations and increased PTH." (PMID 34360805, 2021). "Absence of dentin matrix protein 1 (DMP‐1) and phosphate‐regulating gene with homologies to endopeptidases on the X chromosome (PHEX) influences expression of FGF‐23 in bone and mutations in the encoding genes result in congenital hypophosphatemia." (PMID 31485552, 2019). "We hypothesize that the global deletion of Dmp1 is most likely not responsible for the phenotype as other animal models of reduced bone formation or hypophosphatemia such as Hyp mice also display muscle weakness." (PMID 27242547, 2016). "However, Dmp1−/−kl/kl mice display no sign of rickets or osteomalacia, as these mice were never exposed to hypophosphatemia." (PMID 22879941, 2012). "One of the patients had a large dural ectasia, but it is unclear whether DMP1 is normally expressed in the dura mater and whether the lack of DMP1 in this tissue and/or hypophosphatemia contribute to the development of dural ectasia in ARHP." (PMID 20499351, 2010). "A complete lack of DMP1 in the context of normal renal function results in increased circulating FGF23, hypophosphatemia, low 1,25(OH)2vitamin D levels and diffuse osteomalacia/rickets." (PMID 25774916, 2015). "However, a transgenic overexpression of Dmp1 failed to rescue elevated FGF23 levels and hypophosphatemia of Fam20c knockout mice, suggesting the involvement of other mechanisms." (PMID 36246908, 2022).